AHR (aryl hydrocarbon receptor)
Diseases named in the same sentence as AHR in open-access papers (continued):
Sharing a sentence is not in itself a finding about the gene and the disease.
chronic kidney disease (continued). "In our study we investigated the effects of excessive tryptophan intake on the body and tryptophan metabolism-related AhR pathway in healthy rats and chronic kidney disease rats, to study the adverse effects of excess tryptophan." (PMID 37113297, 2023). "Phthalates induce large accumulation of AHR and AHR nuclear transporter (Arnt) in the nucleus, exacerbating chronic kidney diseases." (PMID 36668758, 2022). "The aryl hydrocarbon receptor (AHR) is a transcription factor with roles in detoxification, development, immune response, chronic kidney disease and other syndromes." (PMID 36198709, 2022). "Animal studies: In a constructed adenine diet model of chronic kidney disease, female AHR knockout mice showed inflammatory and pro-fibrotic gene expression and acute tubular injury." (PMID 36668758, 2022). "During chronic kidney disease, AHR is activated and plays an important role in the pro-thrombotic, vasculotoxic and neurotoxic activities of tryptophan-derived uremic toxins." (PMID 35324718, 2022). "For example, the IS and AhR complex affects cellular immunity dysfunction and is involved in the pathogenesis of atherosclerosis by inducing vascular endothelial cell damage in end-stage renal disease patients." (PMID 32867359, 2020). "Endogenous agonists of the transcription factor aryl hydrocarbon receptor (AHR) such as the indolic uremic toxin, indoxyl sulfate (IS), accumulate in patients with chronic kidney disease." (PMID 32244284, 2020). "Recent studies have demonstrated that AhR is linked to cardiovascular disease (CVD), chronic kidney disease (CKD) and renal cell carcinoma (RCC)." (PMID 31488157, 2019). "The AhR antagonist resveratrol (RSV) has been proven to exert a preservative effect on the IS/AhR/MAPK pathway to rescue IS-induced osteoblastogenesis exacerbation in chronic kidney disease patients." (PMID 40496774, 2025). "AhR has profound impact on inflammation and redox status in cells and inhibition of this signaling pathway is known to have beneficial effects in treating chronic kidney diseases, including DN." (PMID 39902076, 2024). "For chronic kidney disease, our previous literature review also found the dual effect of AhR." (PMID 37113297, 2023). "Interestingly, blood serum from patients with chronic kidney disease activates AHR signaling, consistent with evidence that several of the uremic toxins activate the AHR, including the tryptophan metabolite kynurenine." (PMID 35721564, 2022). "In the same way as for uremic toxins, AHR could be the Pharmakon of chronic kidney disease, at the same time being a cure and a poison." (PMID 35324718, 2022). "It was found that the uremic toxin indole sulfate-induced activation of aryl hydrocarbon receptor (AhR) may lead to disruption of the BBB in non-chronic kidney disease AhR–/– knockout mice." (PMID 36741052, 2022). "In addition, the IS level is significantly correlated with both AhR and tissue factor activities in patients with end-stage renal disease (ESRD)." (PMID 31488157, 2019). "Among endogenous ligands, indoxyl sulfate (IS) serves as a core activator of AhR in chronic kidney disease (CKD): IS is actively transported into the cytoplasm via organic anion transporters (e.g., OAT1/3) on the membrane of proximal tubular epithelial cells." (PMID 40735439, 2025). "Our previous study showed increased intrarenal AHR mRNA and protein expression in patients with chronic kidney disease (CKD)." (PMID 39239643, 2024). "So, tryptophan intake may not be the more the better, kynurenine, IS and AhR pathway activation caused by excessive tryptophan metabolism may have adverse effects on the body, especially in patients with chronic kidney disease." (PMID 37113297, 2023). "In patients with chronic kidney disease (CKD) and in animal models of CKD, the transcription factor Aryl Hydrocabon Receptor (AhR) is overactivated." (PMID 35216489, 2022).
chronic kidney disease (continued). "For example, activation of the aryl hydrocarbon receptor (AhR) pathway may contribute to the development of skin lesions (chloracne), atherosclerosis, chronic kidney disease, tumor promotion, pathological immune response, disruption of spermatogenesis and others." (PMID 36548597, 2022). "In mouse models of chronic kidney disease (CKD) and acute kidney injury (AKI), elevated serum IS activates AHR not only in blood vessels, but also in hepatocytes and cardiomyocytes." (PMID 41155173, 2025). "In muscle, targeted deletion of AhR with HSA-MCM-Cre preserved muscle mass and contractile function in a model of chronic kidney disease." (PMID 40663393, 2025). "In fact, such crosstalk between AHR and NF-κβ pathways could contribute to a variety of AHR responses during the different types and stages of chronic kidney disease (CKD)." (PMID 36499247, 2022). "Effects of resistant starch (RS) and placebo supplementation on AhR and NF-κB mRNA expression and IAA plasma values in chronic kidney disease patients on hemodialysis." (PMID 32459282, 2020). "Moreover, patients with chronic kidney disease are permanently exposed to uremic toxins from the kynurenine pathway, which could be mediated by activation of transcription factor aryl hydrocarbon receptor (AhR)." (PMID 31380290, 2019). "Indoxyl sulfate (IS), an agonist of aryl hydrocarbon receptors (AhR), can accumulate in patients with chronic kidney disease, but its direct effect on bone is not clear." (PMID 38297036, 2024). "Moreover, macrophages from chronic kidney disease (CKD) patients exposed to the uremic toxin IS displayed inflammation through activation of the AhR/NF–κB/MAPK cascade, in a process that induced the mature IL-1β production without activating NLRP3 inflammasome." (PMID 39211042, 2024). "On the other hand, modifying AhR and CYP1A1/2 expression/activity in particular pathological states may be a useful strategy in the therapy of chronic kidney disease and cardiovascular diseases evoked by toxic tryptophan indole metabolites." (PMID 37233670, 2023). "For example, kynurenine, serotonin and indole derivatives may bind to aryl hydrocarbon receptor (AHR), a cytoplasmic ligand-activated transcription factor, to trigger oxidative stress, inflammation in chronic kidney disease." (PMID 34157945, 2021). "The activation of AhR by TCDD may also induce inflammatory responses of kidney tubular cells, and inflammation plays an important role in the pathophysiology of chronic kidney disease (CKD)." (PMID 26963719, 2016). "Patients with chronic kidney disease (CKD) had higher AhR levels than those without CKD (42.8 [IQR: 22.9, 59.2] pg/mL vs. 39.4 [IQR: 18.0, 55.1] pg/mL, p = 0.043)." (PMID 40508196, 2025). "Tryptophan metabolites as ligands can activate AhR signals in many diseases, such as inflammation, oxidative stress damage, cancer, aging-related diseases, cardiovascular disease (CVD), and chronic kidney disease (CKD)." (PMID 34458309, 2021).
metabolic syndrome (60 papers, 2009 to 2026). A cluster of metabolic risk factors for CARDIOVASCULAR DISEASES and TYPE 2 DIABETES MELLITUS. "These authors further reported that in humans, the metabolic syndrome was associated with lowered AHR activity in the feces." (PMID 40687891, 2025). "Other observations in pre-clinical and clinical settings of metabolic syndrome show an association with reduced generation of AHR-activating metabolites by the microbiota, which can be alleviated with AHR agonist-producing Lactobacilli strains." (PMID 39242971, 2024). "Indoles and kynurenines are known ligands of the AHR, whose prolonged activation has been associated with the development of metabolic syndrome, disruption of circadian rhythms, altered glucose and lipid metabolism, and mitochondrial respiratory impairments." (PMID 38652558, 2024). "EPCs disturb metabolic homeostasis through mechanisms such as aryl hydrocarbon receptor (AhR) activation and mitochondrial dysfunction, both of which have been implicated in insulin resistance, T2D, and metabolic syndrome in numerous studies." (PMID 39596044, 2024). "Apart from its involvement in NAFLD and NASH, AhR activation is also associated with dyslipidemia and atherosclerosis." (PMID 38067179, 2023). "Altered levels of tryptophan-derived metabolites have been detected in stool samples from individuals with metabolic syndrome; these changes were associated with reduced AhR activity." (PMID 37512528, 2023). "The development of metabolic syndrome induced by a high-fat diet is associated with decreased Arl hydrocarbon receptor (AhR) ligand levels in mice." (PMID 37894615, 2023). "Fecal samples from patients with metabolic syndrome displayed decreased levels of Trp metabolites and deficiencies in ligands of AhR have been observed in animal models of metabolic syndrome." (PMID 35966699, 2022). "Saccharin/sucralose also markedly decreased microbiota-derived AHR ligands and colonic AHR expression, which are closely associated with many metabolic syndromes." (PMID 33622853, 2021). "AHR has been implicated in several physiologic and pathologic conditions including the development of metabolic syndrome." (PMID 32730300, 2020). "AhR deficiency has been linked with dyslipidemia and dysbalanced glucose homeostasis, two parameters known to contribute to the development of type 2 diabetes in humans." (PMID 32957545, 2020). "Importantly, a recent study has demonstrated that metabolic syndrome is associated with the reduced capacity of microbiota to produce TRP metabolites known to activate AhR." (PMID 40806213, 2025). "Notably, the AHR gene coding for the aryl hydro-carbon receptor was also associated with the regulation of energy metabolism and metabolic syndrome in humans." (PMID 37628596, 2023). "In addition, several studies have linked HFD to decreased AHR signalling, which is an important reason for the impairment of intestinal barrier function as well as the development of metabolic syndrome." (PMID 36555220, 2022). "Thus, certain AHR agonists may be detrimental in causing metabolic syndrome and others might be protective." (PMID 32730300, 2020). "For example, in metabolic syndrome, the observed decline in microbial AHR agonist production occurs alongside broader microbial disturbances." (PMID 41602107, 2026). "Similar results were also observed in fecal samples in mice and in individuals of metabolic syndromes, thus making AhR a potential target for anti-aging and improvement of metabolic disorders." (PMID 40197001, 2025). "AhR can inhibit mitochondrial fatty acid oxidation, negatively impacting lipid metabolism and potentially leading to dyslipidemia." (PMID 41440753, 2025). "In contrast to our findings, some studies have implicated several tryptophan-derived indole metabolites—produced by gut microbiota—in the pathogenesis of metabolic syndrome via activation of the aryl hydrocarbon receptor (AhR) pathway." (PMID 41446296, 2025).
metabolic syndrome (continued). "While causal inference is limited by the cross-sectional design, the findings are consistent with biological mechanisms (e.g., metal-induced oxidative stress, AhR-mediated dyslipidemia) and epidemiological evidence from other cohorts." (PMID 40558877, 2025). "Based on previous work showing that the metabolic syndrome is associated with decreased gut microbial indole production, we expected that RYGB would increase indole metabolites and AhR activation." (PMID 40856156, 2025). "All in all, these results clearly demonstrate that AhR plays an important role in lipid metabolism, driving dyslipidemia and thereby exerting a detrimental effect on related CMDs." (PMID 38067179, 2023). "The top-ranked QTL for the investigated breeds was located within 1MB of ZFAT and HMGA2 genes, while genes overlapping with the human metabolic syndrome were VEGFA, NRXN3, GRIK2, TRIB2, AHR and ISL, potentially related to EMS risk." (PMID 37628596, 2023). "Other studies also indicated that L. reuteri ameliorated metabolic syndrome, celiac disease, and alcohol-induced liver injury by activating AhR." (PMID 35727038, 2022). "Patients with a chronic HFD or metabolic syndrome tend to have lower faecal AHR activity than healthy individuals, which correlates strongly with an unfavourable metabolic phenotype." (PMID 36555220, 2022). "More work is needed to determine the role of ligand-activated transcription factors, such as the AHR, in relationship with environmental pollutants and the metabolic syndrome." (PMID 36295797, 2022). "Reduced AhR activation has been observed in the GM of individuals with metabolic syndrome and intestinal inflammatory disease." (PMID 35966699, 2022). "Collectively, these results suggest that activation of AhR-mediated signaling contributes to H-Exo-induced dyslipidemia and liver damage." (PMID 33431899, 2021). "For instance, individuals with inflammatory bowel diseases (IBD), the metabolic syndrome or celiac disease have decreased fecal concentrations of AhR ligands and reduced AhR activity." (PMID 34540837, 2021). "In another study it was shown that people and animals with metabolic syndrome had reduced levels of AHR agonist activity in fecal samples." (PMID 32730300, 2020). "In metabolic syndrome, the production of AhR agonists by the gut microbiota is reduced and restoring AhR signaling induces beneficial metabolic effects." (PMID 30944419, 2019). "It has been suggested that PAHs could activate the aryl hydrocarbon receptor (AhR) signaling pathway, which may lead to abnormal expression of cytochrome P450 and lead to the development of dyslipidemia." (PMID 40121483, 2025). "Finally, using an in vivo model would provide more biologically relevant insights into AhR function by looking at tissues and cell types impaired in diabetes and metabolic syndromes, such as muscles, liver, and adipocytes." (PMID 39791758, 2025). "In further support to a regulatory role of AHR in energy metabolism, serum AHR ligand activities were found to correlate with obesity and the metabolic syndrome in humans, and a long-term treatment with a subtoxic dose of TCDD exacerbated body weight gain on HFD in mice." (PMID 40687891, 2025). "In metabolic syndrome, production of AhR agonists by gut microbiota is reduced." (PMID 41440753, 2025). "Moreover, AhR is expressed in various cells involved in the pathogenesis of metabolic syndrome, such as enterocytes, hepatocytes, and immune cells." (PMID 38953044, 2024). "Additionally, the GM converts tryptophan and other nutrients into indoles that act via the AHR to reduce inflammation in the metabolic syndrome, especially at the gut level." (PMID 38910152, 2024). "As a blocker of SLC6A14, IDO1 and metabolic syndrome, α-MT can potentially have profound impact on several downstream signaling pathways such as mTOR and AhR because decreased amino acid entry into cells would impair mTOR signaling and decreased generation of kynurenine would suppress AhR signaling." (PMID 39902076, 2024).
metabolic syndrome (continued). "However, AhR antagonists also lower IL-22; therefore, studies of partial agonists/antagonists at this receptor are needed as these agents have the ability to selectively target AhR, avoiding adverse effects such as metabolic syndrome or IL-22 downregulation." (PMID 40729204, 2023). "Additionally, AhR deletion has demonstrated protective effects against high-fat-diet-induced dyslipidemia and vascular dysfunction, potentially by enhancing endothelial nitric oxide synthase/nitric oxide (eNOS/NO) signaling." (PMID 38067179, 2023). "Fecal samples from individuals with metabolic syndrome, obesity, Type-2 diabetes, and chronic intestinal inflammation also have significantly lower levels of microbial Trp metabolites, potentially contributing to reduced AhR activation." (PMID 33916690, 2021). "Conservation of the AHR, and similarities in AHR-mediated dyslipidemia and metabolic disease between rodents and humans, suggest a common mechanism that may identify novel therapeutic interventions for NAFLD which currently has limited treatment options." (PMID 34344994, 2021). "We here report dyslipidemia and dysbalanced glucose homeostasis in AHR-KO mice." (PMID 26664351, 2015). "Moreover, weight gain, one of the most common adverse effects of clozapine, is likely mediated by AhR and could be averted by this receptor’s antagonist, CH-223191, a likely future metabolic syndrome treatment." (PMID 40729204, 2023). "2,3,7,8-tetrachlorodibenzo-p-dioxin (TCDD) is associated with metabolic syndrome (MetS) in humans and elicits pathologies in rodents that resemble non-alcoholic fatty liver disease (NAFLD) in humans through activation of the aryl hydrocarbon receptor (AHR) pathway." (PMID 37789023, 2023). "As a typical aryl hydrocarbon receptor (AHR) ligand, IS activates AHR and then induces endothelial dysfunction, endoplasmic reticulum (ER) stress, podocyte injury, interstitial fibrosis, and glomerular damage in experimental animal models of metabolic syndrome." (PMID 36615841, 2022). "Thus, Trp metabolites may influence metabolic and pro-inflammatory states in metabolic syndrome and obesity through interactions with AhR." (PMID 35966699, 2022). "However, in vivo treatment with the AhR agonist Ficz alleviates the metabolic impairments (e.g., insulin and glucose dysmetabolism, intrahepatic lipid accumulation, and dyslipidemia) in both diet- and genetic-induced metabolic syndrome." (PMID 36144238, 2022). "In diet-induced metabolic syndromes, the microbiota-derived metabolites from dietary sources are important signals and regulators of the host-microbial cross talk; examples are indole metabolites from tryptophan metabolism, which can be potent aryl hydrocarbon receptor (AHR) ligands." (PMID 33622853, 2021). "The inability of the microbiota to convert tryptophan into indoles that activate the aryl hydrocarbon receptor leads to impaired mucosal barrier integrity and decreased GLP-1 secretion, ultimately favoring the development of the metabolic syndrome." (PMID 37374323, 2023). "Previous research had already established a link between the AhR agonist TCDD and dyslipidemia, as it had been reported that TCDD treatment resulted in hepatic steatosis in mice and rats." (PMID 38067179, 2023). "Some scholars have used mouse models to study the role of AhR in metabolic syndrome, but no clear conclusions have been reached, suggesting that the role of AhR on host metabolism is rather complex." (PMID 38953044, 2024). "Confounding the interpretation of the role of AHR in metabolic syndrome or any other diseases in future studies is the observation that not all AHR agonists act in the same fashion." (PMID 32730300, 2020). "However, consistent with an atherogenic profile and symptoms of the so-called metabolic syndrome, HDL levels were significantly lower in AHR-KO." (PMID 26664351, 2015).
metabolic syndrome (continued). "It remains unclear to what extent the systemic lack of AHR - as opposed to its activation by TCDD - affects lipid and glucose metabolism, or parameters of metabolic syndrome, especially when animals age." (PMID 26664351, 2015).